ALB (albumin)
Diseases named in the same sentence as ALB in open-access papers (continued):
Sharing a sentence is not in itself a finding about the gene and the disease.
dengue (71 papers, 2007 to 2026). "As the denominator of the ratio, serum albumin serves as a surrogate marker for the severity of plasma leakage, which is the hallmark of dengue pathogenesis." (PMID 41144436, 2025). "In a cohort of 330 Vietnamese children with dengue, an albumin level ≤ 35 g/L was associated with an increased risk of shock within three days (OR = 3.3; 95% CI: 1.8-6)." (PMID 40337565, 2025). "Overall, there were only few significant associations between DEPs and the following markers of dengue severity: platelet number, hematocrit, plasma albumin, gallbladder wall thickness and the presence of ascites or pleural fluid." (PMID 36595532, 2023). "Shock and/or fluid accumulation was seen in severe dengue patients is believed to be caused by increased endothelial lining disruption leading to intractable leakage of intravascular albumin and other contents into the third space." (PMID 36126060, 2022). "In this and other dengue studies, decreased albumin and protein due to vascular leakage was associated with worsening disease severity." (PMID 28393899, 2017). "Low serum albumin levels have been associated with severe dengue and were more frequent among those who had fatal dengue." (PMID 27391896, 2016). "Low levels of serum albumin have been associated with an increased risk of death for dengue patients and among the general population of critical care patients." (PMID 26090676, 2015). "Although UACRs were increased in the confirmed dengue patients, with a significant time trend showing peak values around the critical period for dengue-associated plasma leakage, urine albumin excretion was also increased in the OFI comparison group." (PMID 23349922, 2013). "Notably, low serum albumin levels have been shown to be associated with progression to severe dengue; therefore, albumin solution should be administered to patients with severe DSS accompanied by unstable hemodynamic conditions." (PMID 39642139, 2024). "In addition, early increased levels of VCAM-1 and SDC-1 were also associated with increased risk of severe dengue, while increased IL-8 and lowered albumin were associated with an increased risk of DHF." (PMID 37838744, 2023). "We hypothesized that i) HA and HS levels will be higher in dengue compared to non-dengue patients on enrolment, ii) HA and HS levels will be associated with markers of disease severity including albumin and platelets and iii) HA and HS will be associated with pro-inflammatory cytokine levels." (PMID 28393899, 2017). "Although the pathogenesis of dengue associated vascular leakage remains unknown, significant losses of albumin and other proteins from the circulating plasma occur, and some washout of proteins from the glycocalyx layer must follow, compromising the function of the layer." (PMID 21886850, 2011). "The 5 most critical features (albumin, APTT, fibrinogen, AST, and platelet count) were incorporated into a visual nomogram for estimating the risk of DSS in pediatric dengue patients." (PMID 40337565, 2025). "Rather, this decline reflects the substantial redistribution of albumin secondary to dengue-induced endothelial injury." (PMID 41144436, 2025). "This integrated metric provides a more comprehensive representation of dengue severity than either lactate or albumin alone." (PMID 41144436, 2025). "Ongoing research is exploring various approaches, including modified fluid regimens, the use of albumin, and innovative alternative treatments to manage better dengue-related complications such as shock and low platelet count." (PMID 41305369, 2025). "Among these, the lactate-to-albumin ratio (LAR) exhibited the strongest predictive value for critical dengue-related outcomes, achieving an area under the curve (AUC) of 0.82 (95% CI, 0.76–0.87)." (PMID 41144436, 2025). "Albumin levels were found to decrease in both children with severe dengue and those with MIS-C children." (PMID 38992604, 2024).
dengue (continued). "The reduction in albumin (ALB) levels following viral infections was documented in dengue virus infection, with a notable decrease in ALB expression observed on day 3 post-infection." (PMID 38739590, 2024). "Serum albumin has also been investigated in various studies, in both adult and pediatric populations, and is proven to be a critical factor predicting severe dengue." (PMID 39039529, 2024). "The results of multivariate regression analysis showed that enzyme AST/ALT > 400 UI/L, serum albumin < 35 g/L and bilirubin TT > 17 μmol/L were independent prognostic indicators of severe dengue." (PMID 34986174, 2022). "The observed rates for six variables (albumin ≤ 2.7 g/dL; AST > 104 U/I; ALT > 141 U/I; platelet count ≤ 97 × 103/μL; PTT > 28.5 s; positive dengue IgM) resulted in risk scores for severe infections of 6.8, 4.8, 9.2, 3.1, 6.8 and 7.9, respectively." (PMID 36006254, 2022). "Multivariate analysis results showed that platelet ≤ 100 G/L and albumin < 35 g/L were independent prognostic indicators of severe dengue." (PMID 34986174, 2022). "It was noteworthy that the serum albumin as prognostic indicator for severe dengue from early phase of the disease." (PMID 34986174, 2022). "The results of our study showed that a decreased serum albumin < 35 g/L was a predictive indicator for severe dengue in both phases of the disease." (PMID 34986174, 2022). "Status decreased serum albumin has also been recognized indirectly reflect the increase in vascular permeability and lead to plasma leakage and shock in dengue disease." (PMID 34986174, 2022). "We would support the 2011 SEARO dengue guideline recommendation that a serum albumin concentration of 3·5 g/dL or lower, or a reduction by 0·5 g/dL during the febrile phase compared with baseline, is associated with progression to severe disease." (PMID 33640077, 2021). "In our meta-analysis, serum albumin concentration during the febrile phase was significantly lower in individuals with severe dengue than in those with uncomplicated dengue." (PMID 33640077, 2021). "When comparing patients with primary dengue to patients with secondary dengue, the albumin and hemoglobin concentration as well as the relative neutrophils and monocytes counts were significantly decreased on the day of defervescence." (PMID 32544159, 2020). "Plasma concentrations of albumin and fibrinogen decreased in dengue patients while increased in OFI." (PMID 32544159, 2020). "On D0, the dengue group had lower albumin and fibrinogen plasma concentrations, as well as lower WBC, neutrophil and platelets counts." (PMID 32544159, 2020). "The rates of change of albumin, fibrinogen, lymphocytes, platelets and TT were shown to be significantly different between dengue and OFI patients in the febrile phase." (PMID 32544159, 2020). "In the post-defervescence phase, dengue patients had decreased albumin and fibrinogen median plasma concentration, a decreased PT, an increased TT as well as elevated AST, ALT, vWF plasma concentration and relative lymphocytes count." (PMID 32544159, 2020). "Reduction in albumin and cholesterol levels seen between the completion of day 3 and day 4 were highly valid predictors of entering into critical phase in dengue hemorrhagic fever." (PMID 30935373, 2019). "In all dengue patients and the DHF subgroup, there was a significant inverse association between HA and, albumin, protein and platelet count." (PMID 28393899, 2017). "Enrolment HA inversely correlated with serum albumin, protein and platelets in all dengue and DHF (p < 0.05)." (PMID 28393899, 2017). "Dengue with warning signs and severe dengue patients had lower platelet counts, lower plasma albumin levels and higher frequencies of clinical signs of increased vascular permeability when compared to patients with mild dengue." (PMID 28542641, 2017).
dengue (continued). "Higher frequencies of low albumin levels (<3.5 g/dL) were detected among the severe dengue cases (47.5 %) compared with the control group (20.0 %) (X2 = 4.19; p = 0.04)." (PMID 27717314, 2016). "In patients with severe dengue, colloids including dextran and 5 % albumin were used as additional fluid resuscitation." (PMID 26832147, 2016). "Assessment of patient management and outcomes during hospitalization demonstrated that a significant proportion of patients with dengue shock and/or organ failure received albumin as fluid resuscitation (p <0.001) and antibiotics (p = 0.017)." (PMID 27564863, 2016). "Regarding the management and outcomes of the study patients, a significantly higher proportion of patients with dengue shock received 5% albumin (P <0.001) and blood components (P = 0.005) compared to patients without dengue shock." (PMID 27196051, 2016). "Hematocrit, albumin, hepatic transaminases, platelet count, and sodium concentrations are laboratory parameters that are routinely checked in the management of dengue patients as recommended by the WHO." (PMID 27391122, 2016). "Overall, dengue-positive patients had lower median total cholesterol and albumin levels than patients with OFI on all days of illness." (PMID 26334914, 2015). "Our results showing daily cholesterol levels decreasing alongside daily albumin levels in dengue-positive patients, especially among patients with severe dengue, supports this idea." (PMID 26334914, 2015). "Platelets, albumin and fibrinogen are all part of the blood compartment in which dengue targets monocytic cells to replicate." (PMID 25768297, 2015). "Levels of albumin in plasma (p = 0.03) and platelet counts <100.000/mm3 (p<0.01) were significantly related to severe dengue and dengue with warning signs respectively." (PMID 24978469, 2014). "We measured formal urine albumin to creatinine ratios (UACRs) in daily samples obtained from a large cohort of children with suspected dengue recruited at two outpatient clinics in Ho Chi Minh City, Vietnam." (PMID 23349922, 2013). "Timing, localization and relation to dengue severity of the ultrasonography findings were determined, as well as the relation with serial hematocrit and albumin values." (PMID 23785539, 2013). "A predictive model to distinguish pediatric leptospirosis from dengue was generated using three variables: the absolute neutrophil count, plasma albumin, and aspartate aminotransferase levels in the first 72 hours of illness." (PMID 18160980, 2007). "A higher probability of leptospirosis compared to dengue was independently associated with higher ANC, lower albumin levels, and AST levels between 30–80 IU/ml on presentation." (PMID 18160980, 2007). "We present the case of a woman from an area endemic for dengue with Guillain-Barré syndrome with a disability scale of 4/6 on the Hughes scale, confirmed by albumin-cytological dissociation, and previous infection with dengue virus confirmed with a positive serum ELISA IgM test." (PMID 40498940, 2025). "Nevertheless, LAR integrates lactate with albumin, a biomarker less influenced by short-term metabolic fluctuations, thereby offering a more robust reflection of both metabolic stress and plasma leakage in patients with severe dengue." (PMID 41144436, 2025). "Albumin levels decreased in 58.82% of children with severe dengue and in 50% in MIS-C." (PMID 38992604, 2024). "For laboratory parameters measured during the early phase, patients with a relative change (increase or decrease) in hematocrit level ≥ 10% and serum albumin < 35 g/L had greater odds of developing severe dengue (OR 3.68, 95% CI 1.15‒11.74 and OR 8.10, 95% CI 2.55‒25.72, respectively)." (PMID 39039529, 2024). "In our study, we reported significantly low mean serum albumin in those with severe dengue." (PMID 35251455, 2021).
dengue (continued). "Altered vascular permeability, accompanied by plasma and albumin leakage, is a common feature of dengue pathophysiology, organ enlargement or increase in weight could be a consequence of fluid accumulation in the interstice." (PMID 34578117, 2021). "In the febrile phase, the day-to-day rates of change in serum albumin and fibrinogen concentration, along with platelet counts, were significantly decreased in dengue patients compared to OFI, while the day-to-day rates of change of lymphocytes (%) and thrombin time were increased." (PMID 32544159, 2020). "In addition, laboratory parameters including aspartate aminotransferase (AST) level, alanine aminotransferase (ALT) level, platelet count, serum hematocrit, and serum albumin level are used as markers of dengue severity." (PMID 30332476, 2018). "Nadir levels of platelet and serum albumin were also lower in patients with severe dengue." (PMID 28732476, 2017). "The significant inverse relationships between HA, with albumin and protein respectively further suggest glycocalyx disruption could increase microvascular permeability and vascular leakage in dengue." (PMID 28393899, 2017). "In our study, increased liver enzymes and albumin levels correlated with severe dengue." (PMID 28827898, 2017). "A low serum albumin was more likely in co-infection compared to isolated dengue (p<0.001) and may, therefore, serve as a predictor of associated scrub typhus in dengue patients." (PMID 27413521, 2016). "In addition, patients with platelet counts <50.0 × 103 cells/μL (p = 0.012) and albumin <3.5 g/dL (p = 0.001) were also more likely to have dengue shock and/or organ failure." (PMID 27564863, 2016). "However, patients with dengue shock and/or organ failure had significantly lower platelet counts (p <0.001) and albumin levels (p <0.001)." (PMID 27564863, 2016). "Moreover, previous studies showed albumin level <3.5 g/dL in dengue fever (DF) and DHF patients, which is in contrast with WHO criteria that use 3.5 g/dL to differentiate patients with and without plasma leakage." (PMID 27391122, 2016). "In addition, median total cholesterol and albumin levels were lower in severe dengue cases than in mild dengue cases over the course of illness." (PMID 26334914, 2015). "Simple linear regression analysis showed that age, systolic blood pressure, and triglyceride level to be negatively correlated with platelet count, while serum albumin and cholesterol levels were positively correlated with platelet count in all of the dengue patients." (PMID 25674854, 2015). "Simple point-of-care tests to quantify urinary albumin excretion are also now available, and could potentially provide useful information for clinical management of suspected dengue cases." (PMID 23349922, 2013). "The adult dengue patient also had lower platelet counts, prothrombin time and serum albumin levels." (PMID 24138072, 2013). "Therefore, decreased tryptophan levels detected in dengue patients may be related to decreased albumin, which was supported by the positive correlation observed between the two measures." (PMID 41159750, 2025). "Hence, elevated lactate levels reflect anaerobic metabolism and tissue hypoperfusion, while low serum albumin levels may indicate systemic inflammation, fluid redistribution, and liver dysfunction, which are central to the pathophysiology of dengue shock." (PMID 41144436, 2025). "Compared to patients with isolated dengue, those with co-infection had higher pulse rate, lower systolic blood pressure, normal leucocyte counts, higher levels of liver enzymes, greater prolongation of partial thromboplastin time (aPTT) and lower serum albumin." (PMID 27413521, 2016). "Previous studies have examined strategies to distinguish between dengue and leptospirosis on the basis of clinical and traditional laboratory parameters, including petechial counts on a standardized tourniquet test, total leukocyte count, aspartate transaminase, and albumin level." (PMID 24444080, 2014).
dengue (continued). "Although significant differences in urine albumin excretion might have been detected using timed urine collections, it would not be feasible to apply this technique to large-scale community based assessments of children with suspected dengue." (PMID 23349922, 2013). "Early indicators of severe dengue include laboratory findings such as elevated c-reactive protein (CRP), elevated aspartate aminotransferase (AST), decreased serum albumin, and decreased platelet count." (PMID 39899203, 2025). "In the first three days of the disease, the results of univariate logistic regression analysis showed that the indicators related to severe dengue were hematocrit > 0.4 l/L, platelet ≤ 100 G/L, AST/ALT > 200 U/L, serum albumin < 35 g/L." (PMID 34986174, 2022). "In this study, we have shown that monitoring serum albumin, AST, and ALT during the febrile phase of illness, in addition to the warning signs detailed in the 2009 WHO guidelines, could enhance the ability to predict the risk of a patient developing severe dengue." (PMID 33640077, 2021). "Considering the other laboratory parameters, dengue patients had higher levels of liver transaminases and CK, but lower WBC, and comparable levels of albumin." (PMID 32063229, 2020). "The dengue patients generally had higher UACRs than the OFI patients, but microalbuminuria, using the conventional cutoff of 30 mg albumin/g creatinine discriminated poorly between the two diagnostic groups in the early febrile phase." (PMID 23349922, 2013). "We found that the combination of 3 laboratory values early in illness-ANC, albumin, and AST-provided the best ability to distinguish between leptospirosis and dengue among children with acute undifferentiated febrile illnesses presenting to the hospital." (PMID 18160980, 2007). "A systematic review and meta-analysis identified key biomarkers predictive of severe dengue manifestations, including elevated levels of CRP, AST, IL-8, and decreased albumin levels for DHF, and increased levels of VCAM-1, syndecan-1, AST, and CRP for severe dengue (SD)." (PMID 40100920, 2025). "Our study showed decreased level of serum albumin in dengue-positive cases that is 23.4% of total dengue-positive group as compared to dengue-negative group." (PMID 39741523, 2024). "From day 4–6 of the disease, the results of univariate logistic regression analysis showed that the indicators related to the prognosis of severe dengue were platelets ≤ 50 G/L, AST/ALT > 400 U/L, serum albumin < 35 g/L, bilirubin TT > 17 μmol/L, PT <70% and fibrinogen < 2 g/L." (PMID 34986174, 2022). "On admission, severe dengue patients in our study cohort were found to have significantly lower serum albumin levels as compared to the non-severe dengue group." (PMID 36126060, 2022). "Mean SGOT, SGPT ALP, total bilirubin and direct bilirubin was significantly higher and albumin levels were significantly low among severe dengue patients when compared with dengue with and without warning signs." (PMID 35251455, 2021). "Caveolae-mediated albumin transcytosis has also been shown to be increased in endothelial cells during dengue virus infection, although the molecular mechanism has not been elucidated." (PMID 29419739, 2018). "The serum albumin levels were significantly lower in co-infection as compared to isolated dengue (3.0 vs 3.9 g/dl; p < 0.001) but not with isolated scrub typhus (3.0 vs 2.9 g/dl; p = 0.95)." (PMID 27413521, 2016). "Furthermore, patients with severe dengue had significantly lower platelet counts (median [IQR]: 41.5 [11.2–63.5] × 103/μL vs. 90.0 [56.0–145.5] × 103/μL, p < 0.001] and albumin levels (median [IQR]: 3.6 [3.1–4.2] g/dL vs. 4.3 [4.0–4.5] g/dL, p < 0.001)." (PMID 26832147, 2016). "Standardized regression coefficients for the correlation of platelet count with serum albumin concentrations after adjusting for continuous covariates on the first day of hospitalization for dengue fever including diabetics and non-diabetics." (PMID 25674854, 2015).